ALKBH7 (alkB homolog 7, RNA demethylase)
Diseases named in the same sentence as ALKBH7 in open-access papers (continued):
Sharing a sentence is not in itself a finding about the gene and the disease.
tumor (8 papers, 2021 to 2025). "In light of the immunosuppressive nature of the tumor microenvironment and the clinical heterogeneity, we utilized multiple datasets and algorithms to confirm the association between ALKBH7 and immunity in HNSC." (PMID 39400540, 2024). "Moreover, ALKBH7 may influence tumor-associated metabolic pathways by upregulating oxidative phosphorylation and fatty acid metabolism pathways." (PMID 39400540, 2024). "This inference was based on previous evidence linking NLRP3 inflammasome activation and ALKBH7-mediated mitochondrial stress to immune modulation within the tumor microenvironment." (PMID 41373809, 2025). "These contrasting roles highlight the complex contribution of ALKBH7 to BC progression and its potential as a context-specific biomarker of tumor behavior." (PMID 41373809, 2025). "Next, the role of ALKBH7 in immunoregulation and tumor microenvironment development was evaluated and the correlation between ALKBH7 and therapy resistance was also monitored." (PMID 39400540, 2024). "We conducted a thorough evaluation of ALKBH7 and discovered its potential as a tumor suppressor, as well as its significance as a prognostic indicator for patients." (PMID 39400540, 2024). "Western blot and immunohistochemical analysis in HNSC patients from the NMU cohort showed the reduced ALKBH7 expression level in tumor tissues." (PMID 39400540, 2024). "Together, ALKBH7 was significantly differentially expressed in different immune and molecular subtypes of multiple tumor types, suggesting that ALKBH7 is a promising pancancer biomarker involved in immune regulation." (PMID 37654657, 2023). "After adjusting for tumor purity, ALKBH7 expression was significantly negatively correlated with most of the immune markers of divergent types of immune cells in PAAD, PRAD and THCA." (PMID 35222541, 2022). "The strong co-expression of ALKBH7 and NLRP3 suggests a functional association between these molecules that may be critical in shaping the tumor microenvironment." (PMID 41373809, 2025). "By modulating cellular metabolism and immune cell infiltration, ALKBH7 may impact tumor progression and treatment response." (PMID 41373809, 2025). "Rather than triggering immune responses through excessive proliferation, tumor cells may develop resistance to immunotherapy by shifting toward mitochondrial stress, mediated by ALKBH7." (PMID 41373809, 2025). "This duality suggests that ALKBH7 may exert divergent biological functions depending on the molecular background of the tumor." (PMID 41373809, 2025). "Consistently, ALKBH7 could regulate the tumor immune microenvironment through different mechanisms, especially in HNSC, which needed further meticulous experiments to decipher." (PMID 39400540, 2024). "A xenograft tumor model was applied to investigate the function of ALKBH7 in vivo." (PMID 38332576, 2024). "For example, in BLCA, ALKBH7 expression correlated with the pathological stage of the tumor." (PMID 35222541, 2022). "Thus, ALKBH7 may facilitate tumor survival via OXPHOS-induced inflammation and immune modulation." (PMID 41373809, 2025). "In this study, the positive correlation between ALKBH7 and NLRP3 suggests a link between mitochondrial stress and inflammation, contributing to immune suppression in the tumor microenvironment." (PMID 41373809, 2025). "Deserve to be mentioned, NK CD56 bright cells were positively related to ALKBH7, which proved to be correlated with CXCL12 expression in a pancreatic pre-tumor cell model and MARCKS expression in HCC, meanwhile, all of them expressed in various tumor." (PMID 35980268, 2022). "We analysed the correlations between ALKBH7 expression and the TMB, MSI, and tumor stemness index to explore the role of ALKBH7 in the immune mechanism and immune response of the tumor microenvironment (TME)." (PMID 35222541, 2022). "In contrast, the mRNA expression levels of ALKBH7 and FTO were negatively correlated with tumor stage." (PMID 34150745, 2021).
tumor (continued). "In contrast, ALKBH7 was highly expressed in BRCA, KICH, LIHC, and PRAD tumor tissues." (PMID 39400540, 2024). "Genomic abnormalities in ALKBH7 significantly reduced CD8+ T-cell immune infiltration, while CD8+ T-cell depletion significantly reduced immune surveillance capacity and the ability to clear tumor cells." (PMID 39400540, 2024). "Using the TIMER database, the ALKBH7 expression level was also significantly negatively correlated with 44 of 50 T cell markers in PRAD and THCA and with 31 of 50 T cell markers in PAAD after adjusting for tumor purity." (PMID 35222541, 2022). "Notably, the role of ALKBH7 in immune-mediated tumor progression in BC has not been previously characterized." (PMID 41373809, 2025).
ALKBH7 also shares sentences with these, for which no sentence is quoted: infection (1 paper); laryngeal carcinoma (1); non-small cell lung carcinoma (1); prostate adenocarcinoma (1); uterine corpus endometrial carcinoma (1).